APP (amyloid beta precursor protein)
Diseases named in the same sentence as APP in open-access papers (continued):
Sharing a sentence is not in itself a finding about the gene and the disease.
neuroblastoma (continued). "Comparing the potency of these unique GSIs in currently established in vitro and cell-based assays reveals that the extended exo-cell assay more closely mimics that witnessed in a cell-based γ-secretase assay that uses N2A mouse neuroblastoma cells stably expressing the APP substrate (N2A-APP)." (PMID 19490610, 2009). "However, it has only recently been appreciated that in a microglia/APP-expressing neuroblastoma cell co-culture model inhibition of ROS activity with superoxide dismutase or catalase (ROS scavengers) resulted in decreased neuronal cell death." (PMID 17094809, 2006). "In humans, APP is a cell surface protein with signal transduction properties that control the viability, proliferation, migration, and aggressiveness of various cancer cells, such as breast cancer, ovarian cell adenocarcinoma, medulloblastoma, and neuroblastoma." (PMID 36542226, 2022). "Importantly, CBD also decreased APP expression in APP-transfected human neuroblastoma cells by inducing APP ubiquitination through peroxisome proliferator-activated receptor gamma (PPARγ), which was paralleled by a reduction of Aβ peptide expression and increased cell survival." (PMID 36117622, 2022). "Next, we performed experiments in a mouse neuroblastoma N2a cell line stably transfected with amyloidogenic mutant APP hAPPsw gene to further investigate the molecular mechanisms by which chronic Mn treatment affects APP processing for increased amyloidogenic Aβ production." (PMID 33244298, 2020). "In order to confirm this hypothesis and to delineate the influence of γ-secretase inhibition on EV- associated APP-CTFs, we first purified EVs secreted from cell media of vehicle- or γ-secretase inhibitor-treated (D6) C99-expressing SH-SY5Y neuroblastoma (SH-C99)." (PMID 31827783, 2019). "Finally, a new generation of ribozymes (hepatitis delta virus (HDV)) has been used in neuroblastoma cells to reduce the expression of amyloid precursor protein (APP) by 70% and the total secretion of amyloid-beta peptides by 30%, thus raising the possibility of ribozymes as therapeutics in AD." (PMID 28982376, 2017). "Toinvestigate whether hyperglycemia could affect APP level, we treated the human neuroblastoma SH-SY5Y cells with media containing 10 mM or 25 mM glucose to mimic hyperglycemiain vitro and compared with cells treated with 2.5 mM glucose media which served as control." (PMID 23894546, 2013). "To further define APP’s intracellular distribution, we first examined its localization in SH-SY5Y neuroblastoma cells—a model relevant in both developmental and aging contexts." (PMID 40671818, 2025). "CNTN4−/−, APP−/− and CNTN4−/−/APP−/− SH-SY5Y neuroblastoma cell lines were generated by CRISPR-Cas9 gene editing." (PMID 38745463, 2024). "In neuroblastoma (SY5Y) transfectants, researchers found multiple pharmacological hits that reduced the translation of the hybrid APP RNA 5′-UTR transcript by >95%." (PMID 39770511, 2024). "A recent report has also shown that many neuroendocrine cancers, including neuroblastoma, use PRC2 to repress MHC-I antigen-processing pathway (MHC-I APP) genes, thereby evading immune surveillance." (PMID 38992040, 2024). "The ability of the soluble ADAM10 to shed overexpressed and endogenous APP was determined with an ADAM10 knockout cell line and a human neuroblastoma cell line, respectively." (PMID 37266401, 2023). "Taken together, these findings are consistent with those obtained in previous reports from our lab in human neuroblastoma cells, confirming that HSV-1 infection strongly modifies the APP processing and tau phosphorylation state in neuronal cells." (PMID 37317179, 2023). "In neuroblastoma cells, the FMRP level is reduced and hnRNPC can bind to the APP mRNA, resulting in an increase of the APP protein level." (PMID 36552825, 2022). "HuD stabilize the APP mRNA, BACE1 mRNA, and BACE1-AS lncRNA in neuroblastoma cells, leading to Aβ accumulation." (PMID 36552825, 2022).
neuroblastoma (continued). "When we investigated the effects of the protein kinase C activator TPPB on amyloid precursor protein (APP) processing, we used PC12 cells and SH-SY5YAPP695 cells, human neuroblastoma SH-SY5Y cells stably transfected with human wild-type APP695 cDNA." (PMID 36307893, 2022). "Full length, 1133 nt, well defined APP 3′UTR was cloned into a reporter vector and co-transfected with miRNAs into differentiated neuroblastoma SK-N-SH cells." (PMID 35197498, 2022). "We used human neuroblastoma SK-N-SH cells and PC12 cells to study the effect of deprenyl on APP processing." (PMID 36307893, 2022). "BACE1 and TAU were identified as new direct targets for miR-455-3p, with overexpression of miR-455-3p leading to a reduction in the expression of APP, BACE1 and TAU in neuroblastoma cells." (PMID 35008980, 2022). "Expression of APP, BACE1 and TAU were all decreased after overexpression of miR-455-3p in SH SY5Y neuroblastoma cells." (PMID 35008980, 2022). "CHT trafficking is different in wild-type APP (APPwt) and in Swedish mutant APP (APPSwe) SH-SY5Y human neuroblastoma cells." (PMID 35330211, 2022). "To verify the generality of APP regulation by the EDEM1 chaperone protein, we downregulated EDEM1 in SH-SY5Y neuroblastoma cells." (PMID 35008544, 2021). "Here, using biochemical methods applied to human embryonic kidney, HEK293, and SH-SY5Y neuroblastoma cells, we show that EDEM1 is an important regulatory factor involved in APP metabolism." (PMID 35008544, 2021). "In SH-SY5Y neuroblastoma cells, BzATP stimulated the release of APP, and the use of antagonists or knockdown with siRNA confirmed P2X7R dependence of APP release." (PMID 33912064, 2021). "For example, in vitro caffeine decreased Aβ level and Aβ1-42 deposition, and reduced BACE-1 activity in human neuroblastoma SH-SY5Y cells, and inhibited oligomerization of Aβ in N2a/APP cells." (PMID 33562156, 2021). "In a human neuroblastoma cell line (SHSY5Y), elevated Fe3+ can bind to APP mRNA and promote APP translation, and the Fe3+ can activate β-secretase and thus induces Aβ production." (PMID 32266063, 2020). "NgR was overexpressed or knockdown in neuroblastoma N2a cells and APPswe/HEK293 cells to investigate the interaction between NgR and amyloid precursor protein (APP)." (PMID 32331528, 2020). "In APP-expressing neuroblastoma SH-SY5Y cells, both APP itself, APP-CTFs and AICD are present in MVBs and on secreted EVs that were isolated from the culture medium." (PMID 33203181, 2020). "Tolfenamic acid inhibited the transcription factor Sp1, which reduced the transcription of APP and BACE1 in Pb-exposed human neuroblastoma SH-SY5Y cells and decreased Aβ accumulation in APP transgenic mice." (PMID 32517647, 2020). "We also tested the effects of E144 on human neuroblastoma SH-SY5Y cells, stably transfected with wild type APP." (PMID 32028607, 2020). "APP and β-CTF were detected in EVs secreted by APPSwe-expressing HEK293 and neuroblastoma SH-SY5Y cells as well." (PMID 33203181, 2020). "Human neuroblastoma SK-N-AS cells were transfected with the different APP constructs and after treatment with the γ-secretase inhibitor DAPT, the full-length APP, sAPPα, and APP-CTF levels were analyzed." (PMID 31604820, 2019). "Human neuroblastoma cells (SY5Y-APPSw), expressing an aggregation- and AD-prone double mutant of APP, accumulate amyloid as measured by fluorescence of amyloid-bound Thioflavin T. Treatment with 5-μM PNR502 for 2 days reduced their amyloid content 50%." (PMID 31920540, 2019). "To examine previous reports of biochemical interactions between RAB10 and APP and between SAR1A and APP, we examined the effects of overexpressing and silencing RAB10 and SAR1A on APP processing in mouse neuroblastoma cells." (PMID 29183403, 2017). "Higher β-secretase-mediated APP processing, suggested by a greater ratio of β-CTF: full-length APP, corresponded with an increase in BACE1 protein expression in human neuroblastoma cells." (PMID 28187176, 2017).
neuroblastoma (continued). "In this study we investigated the effects of increased levels of neuronal APP or Aβ on mitochondrial metabolism and gene expression, in human SH-SY5Y neuroblastoma cells." (PMID 28852095, 2017). "To compare APP- versus Aβ mediated mitochondrial toxicity in intact cells we performed an overexpression of APP or BACE1 in human embryonic kidney cells (HEK293) and in a murine neuroblastoma cell line (N2a)." (PMID 28005987, 2016). "However, because most of these studies were conducted using neuroblastoma cell lines or relied solely on the overexpression of exogenous APP, the significance of these different sorting and processing scenarios with respect to APP-dependent functions in the nervous system remained unclear." (PMID 27932950, 2016). "For example, the inflammatory cytokine IL-8 has been shown to increase beta-secretase 1 (BACE-1), amyloid precursor protein (APP) processing and Aβ production in SH-SY5Y neuroblastoma cells." (PMID 27309956, 2016). "Our results contradict the data obtained in APP and PAT1 or PAT1a double transfected COS and neuroblastoma cells." (PMID 25880931, 2015). "SK-N-MC neuroblastoma cell lysates were applied to GST-Tat beads and the bound proteins were eluted and probed by Western blotting with an antibody against APP." (PMID 24312169, 2013). "Association of the apoE protein to the apoE receptor 2 has been shown to trigger the endocytosis of amyloid precursor protein, (APP) in neuroblastoma cells, leading to the production of amyloid beta (Aβ)." (PMID 23799019, 2013). "The inhibition of Aβ generation was demonstrated in multiple cell systems including isolated primary human neurons, human neuroblastoma SH-SY5Y cells and CHO cells expressing human APP." (PMID 23977395, 2013). "Our current study compared the pharmacokinetics of α-secretase APP processing and PKC-α, -δ, and -ε isoform activation by bryostatin-1 and TPPB in SH-SY5Y neuroblastoma cells." (PMID 22700373, 2012). "Here we found that in the human neuroblastoma cell line, SH-SY5Y, Ubiquilin 1 regulates total full-length APP, the ratio of mature to immature APP, as well as PS1 endoproteolysis." (PMID 17718916, 2007). "Moreover, NMN lowered the protein levels of 6E10 (full-length APP, C99), BACE-1, and CTFs in mouse neuroblastoma N2s cells, suggesting a possibility of amelioration in Aβ pathology of NMN by inhibition of BACE-1 activity." (PMID 39394148, 2024). "Given the therapeutic potential and toxicity parameters with minimal or no side effects, we investigated the role of Hup A on APP proteolysis and tau conformation under physiological conditions in human neuroblastoma SH-SY5Y cells." (PMID 39056711, 2024). "Additionally, earlier investigations showed that the amyloid precursor protein (APP), amyloid intracellular domain, and APP-C-terminal fragment are all released by the exosomes of differentiated neuroblastoma cells and primary neuronal culture cells." (PMID 36834471, 2023). "Furthermore, ATRA [X] treatment restores brain-derived neurotrophic factor (BDNF) dependence of neuroblastoma cells, and a BDNF-dependent increase in amyloid precursor protein (APP) gene expression was also observed." (PMID 37247782, 2023). "In one study, in a human neuroblastoma model (SK‐N‐MC), it was found that PA‐mediated GPR40 signalling increased the expression of amyloid precursor protein (APP) and the catalytic enzyme BACE1, producing Aβ peptide through mTOR/p70S6K1‐mediated HIF‐1α expression and NF‐κB activation." (PMID 36321333, 2023). "Many pro-inflammatory cytokines have been shown to upregulate APP in human neuroblastoma cells and non-neuronal cells such as human astrocyte cultures, as well as in the mouse brain." (PMID 37513235, 2023).
neuroblastoma (continued). "In to understand the biology and fate of the ηCTF fragment, we expressed it in human neuroblastoma cells (SH-SY5Y) and analyzed its expression by western blot using APP-Cter and the WO2 antibodies targeting, the carboxy terminal end of APP and the amino-terminal part of Aβ peptides, respectively." (PMID 36930302, 2023). "In addition, nano-emulsions of naringenin downregulated APP and β-secretase (BACE1) expression in Aβ-induced neurotoxicity in a human neuroblastoma cell line (SH-SY5Y)." (PMID 38204816, 2023). "In this study, plasma from BBR-supplemented goats had an increased concentration of negative APP and decreased levels of the positive APP, which agrees with in vitro studies in mouse neuroblastoma N18TG2 cell line and in human neuroblastoma SH-SY5Y cells." (PMID 35202329, 2022). "Exposure of neuroblastoma cells to toxic Aβ1-42, the APP cleavage product, did not alter protein or mRNA levels of CHCHD6, mitofilin, or CHCHD3." (PMID 36104602, 2022). "Similarly, other studies have shown that amyloid precursor protein (APP), APP-C-terminal fragments, and amyloid intracellular domain were all secreted from exosomes in differentiated neuroblastoma and primary neuronal culture cells." (PMID 34368812, 2021). "In Neuro2a neuroblastoma cells, ORV induced caspase-3-dependent cell death and autophagy, and inhibited γ-secretase, one of the key enzymes involved in the production of β-amyloid (Aβ) from the amyloid precursor protein (APP)." (PMID 34299485, 2021). "Normal neuroblastoma cells N2a, SH-SY5Y cells and APP overexpressed cells 7PA2 were chosen." (PMID 32107408, 2020). "To investigate if BrainPhys culturing could further increase the neuronal phenotype and secretion of APP cleavage products in this cell line, we cultured SH-SY5Y neuroblastoma cells in BrainPhys medium." (PMID 31953468, 2020). "Acitretin was reported to increase the levels of the α-secretase (ADAM10) of amyloid-β protein precursor (AβPP), driving the non-amyloidogenic pathway in neuroblastoma cells with reduction in Aβ levels in APP/PS-1 AD model mice." (PMID 31884477, 2020). "Additionally, we found that ~70% of APP CTFs colocalized with GFP-LC3, further supporting the important role of autophagy in the degradation of APP CTFs in the neuroblastoma cells." (PMID 33203136, 2020). "We first measured the concentration of Aβ peptides in the culture medium of neuroblastomas that were transfected or not with a plasmid overexpressing wild-type APP." (PMID 33370284, 2020). "Using the transgenic APP/PS1/Tau triple transgenic AD (3×Tg-AD) mouse model and mouse-derived microglia and neuroblastoma cell lines, we found that chronic 5-month Mn treatment increased beta amyloid peptide (Aβ) expression and Aβ plaques in the cerebral cortex and hippocampus in these 3×Tg-AD mice." (PMID 33244298, 2020). "For example, knockdown of TMP21 expression by specific siRNA increases the stability and maturation of nascent APP in both non-neuronal and neuroblastoma cell lines, contributing to increased APP level and Aβ generation." (PMID 31379512, 2019). "Additionally, S14 treatment reverted the Aβ-induced reduction in mitochondrial mass in APP/PS1 mice and in the human neuroblastoma SH-SY5Y cells co-exposed to Aβ." (PMID 29458418, 2018). "Similarly, we compared the protection of the SLF moieties in the human neuroblastoma MC65 cell line, which generates large amounts of intraneuronal Aβ by overexpressing the amyloid precursor protein (APP) through Tet-Off transcriptional regulation." (PMID 30103547, 2018). "The impact APP processing in this subcellular localization was assessed by the overexpression of APP or BACE1 in human HEK293 cells (expressing low endogenous BACE1 expression) and N2a murine neuroblastoma cell line." (PMID 29204109, 2017).
neuroblastoma (continued). "Now, β-site APP-cleaving enzyme (BACE1), one of the two enzymes which cleave the amyloid precursor protein (APP) to give beta peptides, has an acidic optimal pH; because of this consideration, the levels of beta peptides have been studied in cultured neuroblastoma cells, treated with lactate." (PMID 27598136, 2016). "This was confirmed in an in vitro neuroblastoma model, since D6 led to autophagic impairment in APPswe overexpressing cells (SH-APPswe), but not in cells only expressing endogenous levels of APP (SH-mock)." (PMID 27138984, 2016). "In particular, we found that infection of SH-SY5Y human neuroblastoma cells and rat cortical neurons with HSV-1 induces multiple cleavages of APP, which result in the intra- and/or extra-cellular accumulation of several APP-Fs with neurotoxic potential." (PMID 24847267, 2014). "We had previously reported that iron efflux from neuroblastoma and primary neurons was promoted by APP and sAPPα in the absence of a ferroxidase enzyme." (PMID 25464026, 2014). "The interaction between endogenous APP and FPN was also analysed by FACS of neuroblastoma cells." (PMID 25464026, 2014). "Others have shown that overexpression of JIP1 decreases Aβ production but these studies were conducted in non-neuronal or neuroblastoma cells overexpressing APP." (PMID 23825109, 2013). "Neither knocking down endogenous BIN1 expression with targeted siRNA nor overexpression of BIN1 in a human neuroblastoma cell line had an effect on APP processing." (PMID 24205320, 2013). "As a first step towards determining whether these sites were functionally important, we determined the histone modification state around this cluster in a human neuroblastoma cell line, SHSY5Y, which expresses human APP mRNA." (PMID 22947103, 2012). "To characterize this postinfection APP processing in neuronal cells, we infected human neuroblastoma cells (SH-SY5Y) and primary rat cortical neurons and monitored APP cleavage by western blot analysis of cell lysates with a panel of antibodies directed against different epitopes of the Aβ domain." (PMID 21085580, 2010). "MC65 is a genetically engineered human neuroblastoma cell line that conditionally expresses a partial (amino-17 residues + carboxyl-99 residues) fusion of the APP protein with the removal of tetracycline (-TC), where C99 is expressed and cleaved by secretases to generate the Aβ peptide." (PMID 39594552, 2024). "Although Pon1 depletion in mouse neuroblastoma N2a-APPswe cells downregulated Phf8 and upregulated APP and Aβ, depletion of Phf8 upregulated Aβ but not APP." (PMID 36899882, 2023). "Therefore, we examined the relationship between HDAC activity and synaptic defects using an HDAC inhibitor (HDACI), BG45, in the human neuroblastoma SH-SY5Y cell line with stable overexpression of Swedish mutant APP (APPsw) and in APP/PS1 transgenic mice during this study." (PMID 35807406, 2022). "In cell culture experiments, using human neuroblastoma cells and mouse mixed cortical neurons, five different oxidized DHA derivatives and the lipid peroxidation products of n-3 and n-6 PUFAs, HNE and 4-hydroxy-hexenal, revealed elevated Aβ and soluble β-secreted APP levels." (PMID 36428494, 2022). "Moreover, in human neuroblastoma SH-SY5Y cells and CHO cells stably expressing human APP, 24-OHC has been shown to inhibit intracellular APP trafficking leading to immature APP retention in the endoplasmic reticulum (ER) without affecting secretase activities, while still suppressing Aβ production." (PMID 34067119, 2021). "Mechanistically, a recent in vitro study with APP695-transfected SH-SY5Y neuroblastoma cells reported that caffeine treatment decreased Aβ levels by shifting APP processing towards the non-amyloidogenic pathway with increased α- and decreased β-secretase activity." (PMID 34913091, 2021).